IFNG (interferon gamma)
Diseases named in the same sentence as IFNG in open-access papers (continued):
Sharing a sentence is not in itself a finding about the gene and the disease.
tumor (continued). "Although production of IFNγ by T and NK cells in cancer microenvironment was required for cytotoxic activity, IFNγ may serve as a pivotal molecule to facilitate tumor tissue homeostasis, promoting cancer evasion." (PMID 34159752, 2021). "Moreover, Y111 increased the cytotoxicity of the expanded Vγ2Vδ2 T cells against various NSCLC-derived tumor cell lines with the releases of granzyme B, IFNγ, and TNFα in vitro." (PMID 34040604, 2021). "Flow cytometry analyses of tumor-infiltrating NK cells from sMIClo and sMIChi tumors validated that NK cells from sMIChi tumors had diminished cytotoxic effector function and marked reduction in the capacity to produce anti-tumor cytokines, such as IFNγ and TNFα." (PMID 34294876, 2021). "In response to interferon γ (IFNγ), lipopolysaccharide (LPS), tumor necrosis factor α (TNFα), and interleukin-12 (IL-12), macrophages can acquire the M1 phenotype, which governs the innate host defense and kills tumor cells in the context of Th1 immunity." (PMID 34300195, 2021). "Moreover, the function of CD8+ T cells was also remarkedly improved by the combination therapy of OVA@SVMAV and aPD-1, as indicated by the flow cytometry analysis of IFNγ+ CD8+ T cells in tumor." (PMID 34452929, 2021). "We then asked whether Gal-9 expression is regulated by immunomodulatory cytokines/factors that are typically present in the TME during an anti-tumor immune response, including IFNβ, IFNγ, and TNFα." (PMID 33547304, 2021). "Wang and colleagues found that CD8+ T cells activated by anti-PD-1 therapy enhanced the lipid peroxidation of tumor cells by releasing interferon gamma (IFN-γ), while the enhanced ferroptosis response could further elevate the immune efficacy." (PMID 33738257, 2021). "Interestingly, IFNγ can activate macrophages to enhance macrophage functions, such as tumor cell cytotoxicity." (PMID 33456564, 2021). "However, we demonstrate that vaccination with either citGRI or citMMP21 stimulated strong Th1 IFNγ responses in mice that overcame any peripheral or tumour mediated regulation to elicit efficient tumour therapy." (PMID 34858415, 2021). "Here, these interactions appear to occur dependent on the phenotype of the ihMθ population in accordance with an increased production of IFNγ and iron sequestration in macrophages depleting the microenvironment, thereby limiting tumor growth while fostering inflammation." (PMID 34829862, 2021). "Indeed, the inclusion of siPD-L1 into an mRNA cancer vaccine delivered via lipid coated calcium phosphate nanoparticles was shown to reduce tumor growth and enhance IFNγ responses." (PMID 34688033, 2021). "Furthermore, IFNγ can modulate many cellular components of the tumor microenvironment to induce promo-tumorigenic effects, limiting its potential use in cancer immunotherapy." (PMID 33671123, 2021). "CD19 is presently thought to be the best accessible target for CAR-T cell treatment in blood cancer, whereas autophagic degradation of GZMB represents a novel method for hypoxic tumor cells to avoid natural killer cell-mediated lysis, and IFNG is important in maintaining immune homeostasis." (PMID 34893051, 2021). "To date, studies investigating the impact of checkpoint inhibitors on MAIT cell functions are limited but targeting MAIT cells with checkpoint inhibitors may help harness their anti-tumour effector functions such as IFNγ and cytolytic molecule production." (PMID 33808058, 2021).
tumor (continued). "Our data thus demonstrate that treatment of some human GBM cells with GSK126 in vitro, results in a reversal of H3K27me3 that allows increased expression of CXCL9 and CXCL10 when induced by IFNγ leading to increased migration of T cells to tumor conditioned medium." (PMID 34336705, 2021). "Interestingly, AHR is involved in the dormancy of tumor cells in response to IFNG, thus promoting tumor immune evasion." (PMID 34566988, 2021). "For example, IFNγ is secreted by activated T cells and NK cells to promote anti-tumour immunity through: enhancing antigen presentation and pro-inflammatory differentiation of macrophages; stabilising Th1 lineage commitment, and; restraining regulatory T cell induction." (PMID 33597595, 2021). "Moreover, the tumor cell killing activity of the heat-inactivated supernatant was substantially restored by the addition of IFNγ and TNFα." (PMID 32666260, 2021). "In a variety of tumor types, the presence of significant baseline T-cell infiltration and interferon gamma (IFNγ)-related mRNA signatures (indicative of increased adaptive anti-tumor responses) has consistently been associated with increased sensitivity to ICIs and improved prognosis." (PMID 34685400, 2021). "Moreover, using the same algorithm, neoantigens predicted from somatic mutations of the genes MSH6, PIGO and AXIN2 observed in the LS-CRC tumour of one of the affected family members, was shown to induce interferon gamma (IFNγ) releasing T cell responses." (PMID 34067951, 2021). "The increase in IFNγ mRNA in the CD11B population prompted us to interrogate if the macrophages present had changed to a less tumor-promoting phenotype since analysis by flow cytometry showed no change in the percentage of the CD11B population infiltrating into the tumors." (PMID 34638488, 2021). "DKK3 may function as a tumor suppressor gene, and SPP1 functions as a cytokine resulting in increased interferon-gamma and interleukin-12 expression, and has been associated with enhanced tumor cell invasion and dissemination in EAC." (PMID 34638363, 2021). "Our results also show that IFNγ and TNFα have opposite effects in the tumor microenvironment." (PMID 34869307, 2021). "Moreover, HDAC2 also promoted IFNγ-induced PD-L1 expression to enhance antitumor immunity and tumor proliferation and metastasis." (PMID 34993131, 2021). "Furthermore, lncRNA IFN-stimulated noncoding RNA 1 (INCR1), transcribed from the PD-L1 locus, is correlated with PD-L1 expression levels in tissues and is involved in regulation of tumor IFNγ signaling." (PMID 34496886, 2021). "CD8+ T-cell tumor infiltration is associated with heightened anti-tumor immunity, and cytotoxic responses in HNSCC, and anti-tumor activity elicited by PI3K inhibition has been shown to be dependent on interferon-gamma (IFN-γ) and IL-17." (PMID 33668795, 2021). "Similarly, disruption of Ezh2 activity or depletion of Helios in Tregs leads to Foxp3 instability with an increased expression of effector cytokines like IFNγ and TNFα, enhanced anti-tumor immunity, and decreased tumor growth and progression." (PMID 34394124, 2021). "This sustained immune activation elicited by combination therapy was further supported by functional analysis demonstrating a significant increase in activated bifunctional CD8+ T cells producing both IFNγ and TNFα at day 25, which also correlated with tumor size reduction." (PMID 34446712, 2021). "Also, 0.6 ± 0.3% of all live cells in the tumours of pHIFU + ICI-treated subjects were CD8+IFNγ+ T cells, whereas this was only 0.2 ± 0.1% in controls." (PMID 34229458, 2021). "Since the patient-specific kc values were calculated from the IFNγ expression at four time points, taking the three most significant tumor micro-environment features as inputs into the C-SBINN required using a total of six experimental measurements for each patient." (PMID 34267327, 2021).
tumor (continued). "In addition, IL-36γ promoted qualitative changes such as increases in IFNγ production by CD8+ tumor-infiltrating lymphocytes and DCs and decreased M2 TAMs and MDSCs." (PMID 33538860, 2021). "On the other hand, T cell-derived IFNγ may prevent tumor killing by NK cells via enhanced MHC-I expression." (PMID 34201655, 2021). "However, previous studies have suggested that lymphocytes interplay in controlling tumor growth via secreting cytokines such as interferon gamma (IFN-γ) and tumor necrosis factor alpha (TNF-α)." (PMID 33989285, 2021). "The cytokine levels also did not change in response to the decrease in FAP+ cells, which supports the latter hypothesis that FAP reduces the response of tumor cells to tumor necrosis factor alpha and IFNγ." (PMID 34490078, 2021). "Lower amounts of IFNγ+ T cells are also reported among the tumor-infiltrating lymphocytes." (PMID 33717088, 2021). "Likewise, interferon-gamma (IFNG) response genes are another well-studied mRNA metric for evaluating the potential anti-tumor activity." (PMID 35111196, 2021). "Helped CD8+ T cells then upregulate molecules such as granzyme A, granzyme B, perforin, fas ligand, trail, and IFNγ, which play roles in cytotoxic effector function, and may help delay distal tumor growth." (PMID 36405502, 2021). "IFNγ is a cytokine that is generally present in the tumor microenvironment, which contains CTLs." (PMID 34458148, 2021). "Furthermore, these TIMEs lead to the independent regulation of PD-1/PD-L1 (programmed cell death protein 1/PD-1 ligand), a popular axis targeted by immune checkpoint therapy, in response to ongoing anti-tumor immunity and the presence of interferon-gamma." (PMID 34064795, 2021). "Interestingly, IL-12 did not exert its effect in this model by recruiting endogenous T cells to the tumor or rely on host IFNγ producing cells." (PMID 34177932, 2021). "However, co-treatment with TNFα and IFNγ induced whole tumour cell apoptosis by 37.6% in STING KO mice." (PMID 34285232, 2021). "Priming pro-tumor neutrophils with IFNγ and TNFα could convert them to tumor-suppressing cells even in the presence of G-CSF and IL-6 by restoring the PI3K and p38 MAPK signaling pathways." (PMID 34572138, 2021). "Finally, the majority of γδ T cells can directly kill tumor cells through granzyme and perforin secretion or indirectly through IFNγ and TNF production." (PMID 33801234, 2021). "Previous experimental evidence revealed that the presence of a high T cell infiltration, an interferon-gamma (IFN-γ) signature, checkpoint gene (e.g., PD-1 and PD-L1) expression, or a high tumor mutational load (TML) could favor a treatment response." (PMID 33946047, 2021). "A previous study confirmed that sustained low-level expression of IFNγ could promote tumor development 29, so we could consider that IFNγ is a “double-edged sword” in antitumor efficacy in the MB49 model." (PMID 33753998, 2021). "Increased HLA induced by IFNγ, which counteracts HLA downregulation by the tumor, could contribute to higher effectiveness of immunotherapies in MCC patients." (PMID 35003017, 2021). "The correlated expression patterns in tumor and immune cells as seen here fit with the current perception, that acquired PD-L1 upregulation seems to be driven by distinct anti-tumor immunity factors in the microenvironment, such as interferon gamma (IFN-γ), potentially acting on both compartments." (PMID 33918309, 2021). "IFNγ secretion from mainly CD8 T cells induces an increased anti-tumor response by stimulating antigen expression and chemokine production, though also induces increased expression of the transmembrane protein PD-L1 as a self-protective mechanism to avoid excessive damage from the inflammation." (PMID 33916646, 2021).
tumor (continued). "Cytokines (e.g., interferon gamma (IFN-γ) and ILs) are commonly used in cancer immunotherapy due to their wide range of anti-tumor activity, such as stimulating immune effector cells, increasing tumor cell recognition and activating cytotoxic cells." (PMID 34575943, 2021). "Although indirectly associated to the IFNγ pathway, loss of the protein tyrosine phosphatase Ptpn2 was correlated to enhanced levels of antigen-loaded MHCI molecules on the surface of tumors and to sensitivity of tumor cells to immunotherapy." (PMID 33406696, 2021). "Furthermore, tumour-derived TGF-β has been shown to negatively impact on the mitochondrial function (via phosphorylation of Smad proteins), resulting in compromised IFNγ production and the reduced anti-tumour activity of T cells." (PMID 33925949, 2021). "In this study they found that this combination therapy concurrently decreased tumour growth whilst significantly increasing proinflammatory TNFα, IFNγ and MCP-1 cytokine and chemokine expression, concomitant with a significant reduction in the M2-polarised macrophage population." (PMID 34944870, 2021). "Similarly, stimulation of DCs via TLR-4 activation and tumor antigens significantly increased cytotoxic CD8+IFNγ+ T cells in vivo." (PMID 34124272, 2021). "Epithelial-Mesenchymal Transition (EMT), interferon gamma response, IL2/STAT5 signaling and some other pathways are activated in the high risk group, which manifest immune suppression, drug resistance, tumor evasion." (PMID 33928021, 2021). "The observed effect might derive from an IFNγ response by tumor cells or host immune cells, particularly TAM." (PMID 34220848, 2021). "We hypothesized that SHP2 blockade in cancer cells could augment their response to IFNγ and tested the response of OVCAR-8 tumor spheroids to recombinant human IFNγ (rhIFNγ) in the presence of SHP099 or TNO155." (PMID 33446805, 2021). "In addition, treatment increased multiple immune-related gene sets in the tumor tissue of donor #1 group, including IFNγ-mediated signaling pathway, T-cell activation, MHC-II protein complex, DC differentiation, and Th1-type immune response." (PMID 34589427, 2021). "Compared with WT mice, IFNγ-/- mice had higher tumor incidence." (PMID 33456564, 2021). "Alternatively, CD103+CD8+ T cells may have a role in tumor suppression beyond direct cytotoxic killing through the secretion of TNFα and IFNγ, or the recruitment of other immune cell populations that in turn may limit tumor growth." (PMID 33968059, 2021). "Indeed, in vitro studies showed that JAK2 inhibition impaired IFNγ-mediated PD-L1 upregulation at mRNA and protein level in tumor cells." (PMID 33804419, 2021). "Flow cytometry and ELISPOT analyses indicated that CC-SnT-TRP2 OMVs elicited a strong increase in the numbers of IFNγ+ cytotoxic T lymphocytes and IFNγ production, confirming that OMVs displaying a specific tumor antigen can induce a strong adaptive immune response." (PMID 33824314, 2021). "In this phase I clinical trial, LDRT paired with immunotherapy promoted CD4+ T cell infiltration, induced de novo inflammation, and promoted tumor regression in an IFNγ-dependent manner, thus supporting the rationale for combining LDRT with immunotherapy in tumors with low T cell infiltration." (PMID 34975924, 2021). "There are multiple potential reasons for patients not responding to ICIs: lack of CD8+ T cell tumor infiltration, low tumor cell mutational burden, and low IFNγ signature, or so-called ‘cold’ TME." (PMID 34578321, 2021). "PD-L1 expression could be activated in tumor cells either by oncogenic signaling or by inflammatory cytokines, particularly interferon gamma, as a result of the adaptive immune response." (PMID 33728352, 2021). "Interestingly, we found that IFNβ facilitated Gal-9 secretion from tumor and myeloid cells, and its secretion was further augmented by the presence of IFNγ." (PMID 33547304, 2021).
tumor (continued). "In addition, the down‐regulation of NKG2D ligands in tumor cells induced by IFNγ alters the tumor cell phenotype from NK cell‐sensitive to NK cell‐resistant." (PMID 33491334, 2021). "In addition, PDT can enhance ferroptosis and sensitise tumour cells to ferroptosis by recruiting immune cells to secrete interferon-gamma." (PMID 34912804, 2021). "Additionally, PD-L1 is expressed not only on the surface of tumor cells but also on immune cells in tumor tissues, and its expression can be affected by cell growth mediator such as IFNγ." (PMID 34603277, 2021). "Furthermore, we also measured the production of IFNγ in the tumor-infiltrating CD8+ T cells in the treatment of PMA/ionomycin." (PMID 34446716, 2021). "Moreover, their findings showed that the deprivation of methionine promoted CD8+ T cell apoptosis and reduced its IFNγ and TNFα production, whereas methionine supplement improved tumor-infiltrating CD8+ T cell cytokines production and anti-tumor responses." (PMID 35087832, 2021). "Moreover, we observed an increased trend of PD-L1 expression in 4T1 cells when SHP2 gene was knocked out, suggesting that IFNγ signaling was enhanced by SHP2 depletion in tumor cells." (PMID 33446805, 2021). "Addition of TGF-β during expansion (TGF-β imprinting) does not affect their proliferation and paradoxically and results in hyperinflammatory NK cells that produce large amounts of IFNγ, TNFα, and GM-CSF when co-cultured with tumor cells even in the presence of TGF-β." (PMID 33766099, 2021). "The number of tumor-specific IFNγ-producing cells was measured using the ELISPOT assay." (PMID 33671258, 2021). "We found Y111, but not CD3 Isotype or PD-L1 mAb could significantly enhance the secretions of IFNγ, TNFα, and granzyme B from the expanded Vγ2Vδ2 T cells in the presence of tumor cells." (PMID 34040604, 2021). "Th1 cells could increase the expression of anti-tumor immunity genes to produce more IFNγ and TNFα in the lung." (PMID 34887858, 2021). "We speculated that the released IFNγ and TNFα could also mediate killing of tumor cells in a cell contact-independent manner." (PMID 32666260, 2021). "In order to investigate whether the Immunomodulatory mAbs induce tumor cell lysis through the activation of hPBMCs, we examined the release of Interleukin 2 (IL-2) and Interferon gamma (IFN-γ)." (PMID 34201082, 2021). "Besides, CD8 T cells also produce IFNγ that enhance the expression of MHC class I antigens in tumor cells, making them better targets for CD8 T cells." (PMID 34136488, 2021). "In addition, the tumor-infiltrating CD8+ T cells from Tagln2−/− DC-injected mice expressed a lower level of IFNγ than that in WT DC-injected mice." (PMID 33731208, 2021). "Our study showed that high expression of GOLT1B induced the increase of PD-L2 expression in CRC cells, which could induce the apoptosis of tumor-infiltrating T lymphocytes and inhibit the level of IFNγ." (PMID 34059062, 2021). "While IFNα and IFNβ show anti-tumour effects, IFNγ is a double-edged sword in cancer." (PMID 34445385, 2021). "Moreover, the activity of IFNγ in the tumour microenvironment is complex, with interferons produced by tumours conferring resistance to immune checkpoint blockade." (PMID 33597595, 2021). "Since interferon-gamma (IFNγ) and tumor necrosis factor-alpha (TNFα) in the tumor environment play a vital role in antitumor activity via the stimulation of tumor-specific cytotoxic T cells, cytolytic responses by CTLs were also observed by immunohistochemistry (IHC) staining." (PMID 34389619, 2021). "However, the combination of the two therapies induced high levels of antigen-specific IFNγ production, indicating the ability of this combination to induce epitope spreading at the tumor site." (PMID 33033852, 2021). "The PBRM1 loss could impair the IFNγ signaling pathway in murine RCC cell lines and thus correlated with a less immunogenic tumor environment as well as resistance to ICB." (PMID 33777757, 2021).